MMP1 (matrix metallopeptidase 1)
Diseases named in the same sentence as MMP1 in open-access papers (continued):
Sharing a sentence is not in itself a finding about the gene and the disease.
breast tumor (23 papers, 2006 to 2025). "Cancer cell proliferation is linked with the MMP-1,−2,−7, and−9, whereas breast tumor metastasis is linked with the MMP-1,−2,−3,−7, and−9 to−18." (PMID 33520928, 2020). "MMP1 expression at least 1+ and higher was detected in 104 (69.8%) of samples in breast tumor cells and in 120 (80.5%) samples of tumor associated stroma (p = 0.04)." (PMID 24972610, 2014). "Mean ± SEM (standard error of mean) for MMP1 expression histoscore in tumor associated stroma was significantly higher compared to breast tumor cells (32.8 ± 3.4 vs. 49.1 ± 5.1, p = 0.05)." (PMID 24972610, 2014). "Our study showed also that both tumoural and stromal MMP-1 expression is associated with breast tumour progression and poor prognosis." (PMID 21835023, 2011). "In summary, our study shows that both tumoural and stromal MMP-1 positivity is associated with breast tumour progression and poor prognosis." (PMID 21835023, 2011). "Therefore, we examined expression of MMP1 on breast tumor tissue as well as tumor associated stroma and correlated them with CTCs in peripheral blood." (PMID 24972610, 2014). "Some studies reported that MMP-1 was mainly secreted by stromal cells, such as OBs and fibroblasts, in prostate and breast tumor microenvironment and promoted cancer cell migration and invasion through PAR-1 signaling." (PMID 34966687, 2021). "MMP1 expression was also significantly increased in aggressive breast tumors and correlates with both tumor size and histological grade." (PMID 33396463, 2020). "MiR-202-3p is downregulated in brain metastases compared to primary breast tumors and directly targets MMP-1." (PMID 33002044, 2020). "Our preliminary bioinformatics analysis revealed that, among the micro-RNA predicted or validated to target MMP1, miR-202-3p is significantly downregulated in brain metastatic lesions compared to the primary breast tumors." (PMID 33002044, 2020). "Both MMP-1 expression and collagenase activity is upregulated in breast tumors carrying PAR1 as compared to normal mammary pads." (PMID 30065181, 2018). "One recent study suggest that the circulating breast tumor cells with EMT markers had significantly increased MMP1 expression." (PMID 28334049, 2017). "The determination of optimal cutoff values for Pit-1 and MMP-1 in breast tumors was done for predicting recurrence." (PMID 25527274, 2014). "We further showed that Pit-1 positively correlated with MMP-1 and MMP-13 expression in 110 human breast tumors, and positive Pit-1 expression also correlated with positive expression of MMP-1 and MMP-13 in tumor cells and fibroblasts." (PMID 25527274, 2014). "The requirement for MMP1 for breast tumor growth was partly attributed to breakdown of the fibrous stroma within the mammary fat pad and partly to the liberation of growth factors present in ECM." (PMID 22439866, 2012). "For clinical validation, while we confirmed elevated expression of SPANXB1 and its downstream effectors (YY1, H3R17me2, MMP1) in both primary breast tumors and brain metastases, the small sample size (n = 5 per group) necessitates validation in larger clinical cohorts." (PMID 40885703, 2025). "In addition, breast tumors showed higher protein levels of MMP-1, -7, -8, -9, -12, and -13 compared with normal breast tissue." (PMID 31534541, 2019). "In addition, one recent study observed that the circulating breast tumor cells with EMT markers had significantly increased MMP1 expression." (PMID 28334049, 2017). "Metastasis progression genes may have different functions in the primary tumour and distant metastasis, for example, MMP-1 promotes vascular remodelling in primary breast tumours and also contributes to lung extravasation." (PMID 26052355, 2015). "Finally, in human breast tumors there is a significant correlation between Pit-1 and MMP-1 and MMP-13 expression in both tumor and fibroblast cells, suggesting a relationship between Pit-1 and MMPs expression in Pit-1-induced metastasis to lung." (PMID 25527274, 2014).
breast tumor (continued). "MMP-1 (interstitial collagenase) has been associated with MDA-MB-231 invasion in vitro, while MMP-3 (stromelysin-1) has been localised around invasive cells of breast tumours in vivo." (PMID 16430785, 2006). "Thus, it is tempting to speculate that high Pit-1 levels in fibroblasts from breast tumors could induce increased MMP-1 and MMP-13 expression, which in turn may increase collagen degradation and facilitate the dissemination of tumor cells to lung." (PMID 25527274, 2014). "Human breast tumors also have lower levels of LPP1 and higher levels of cJUN, cFOS, MMP-1, -7, -8, -9, -12, -13, cyclin D1, and cyclin D3 relative to normal breast tissue." (PMID 31534541, 2019). "We also determined that MMP-1 and MMP-3 mRNA levels were higher in all types of breast tumors than in normal breast tissue." (PMID 31534541, 2019). "In a second gene expression data set of 7 breast tumor and 15 normal stroma samples (GSE8977), we observed the same differential expression for EFEMP1 and MMP1." (PMID 27468688, 2016). "A significant positive correlation between Pit-1 and both MMP-1 and MMP-13 was also found in human breast tumor datasets." (PMID 25527274, 2014). "In addition MMP-1 and MMP-13 positive expression in fibroblasts and tumor cells is positively correlated with high Pit-1 score values in human breast tumors." (PMID 25527274, 2014). "Finally, by immunohistochemistry we correlated Pit-1 with MMP-1 and MMP-13 protein expression in 110 human breast tumors samples." (PMID 25527274, 2014). "Moreover, a few genes involved in modulation of the extracellular matrix (ADAMTS4, MMP1, MMP3, and angiogenesis (MFAP5, SFRP2, SRPK1, VEGF, and CHI3L1) were found to be expressed at higher levels in the primary breast tumors compared with the bone metastases." (PMID 23174366, 2012).
cervical carcinoma (23 papers, 2010 to 2025). A carcinoma arising from either the exocervical squamous epithelium or the endocervical glandular epithelium. "Intersection analysis revealed 18 genes that were significantly differentially expressed, including the five selected biomarkers (MMP1, RNF2, TFRC, SPP1, and CXCL8), which are significantly associated with cervical cancer progression." (PMID 40809844, 2025). "In this study, we identified five ubiquitination-related biomarkers (MMP1, RNF2, TFRC, SPP1, and CXCL8) that are significantly associated with cervical cancer." (PMID 40809844, 2025). "Among these, MMP1 and RNF2 are particularly noteworthy because of their close association with cervical cancer tumorigenesis, particularly in terms of invasiveness and metastasis." (PMID 40809844, 2025). "In summary, MMP1 plays a pivotal role in the initiation and progression of cervical cancer, with its expression and activity modulated by multiple mechanisms, including the ubiquitination pathway." (PMID 40809844, 2025). "Common cell adhesion molecules, such as MMP1 and ADAMTS8, are reported to be associated with invasive metastasis of cervical cancer and to reduce patient prognosis." (PMID 38410799, 2024). "Our IHC results of cervical cancer patients further validated the overexpression of MMP1 in tumor tissue compared to normal tissue." (PMID 38356704, 2024). "On the other hand, in knockdown MMP-1 cervical cancer cell lines it has been demonstrated a reduced invasion ability compared to the control, suggesting that knockdown of MMP-1 is responsible of reduced proliferation, invasion and migration." (PMID 36713871, 2022). "Tian and collaborators showed that MMP1 overexpression and the PPAR signaling pathway were linked to LN metastasis in cervical cancer patients." (PMID 35804810, 2022). "MMP1 greatly promotes tumor cells' migration and invasion and has been reported to correlate with immune cells' infiltrations in breast and cervical cancer." (PMID 35655921, 2022). "MMP1 knockdown inhibited cervical cancer cell proliferation, migration, and invasion, while increasing the expression of epithelial marker E-cadherin and decreasing the expression of the metastasis-associated gene vimentin." (PMID 35804810, 2022). "AKT activation has been further linked to CKII phosphorylation of high-risk E7, leading to the secretion of MMP1 and MMP13 associated with an invasive phenotype of HPV-18-positive C4-1 cervical cancer cells." (PMID 34696321, 2021). "The prognostic values of SPP1, EFNA1, and MMP-1 in cervical cancer have been investigated in previous studies." (PMID 32300605, 2020). "The present study supported previous reports by showing that the high expression of MMP1 was significantly related to poor overall survival in cervical cancer." (PMID 32300605, 2020). "MMP1 is overexpressed in cervical cancer, and knockdown of MMP1 reduced the proliferation and migration of cervical cancer cells, while expression of epithelial marker E-cadherin increased and expression of mesenchymal marker Vimentin decreased." (PMID 30283446, 2018). "This suggests that MMP1 may act synergistically with CXCL8 to collectively drive the malignant progression of cervical cancer." (PMID 40809844, 2025). "In short, the expression of MMP1 was elevated and may serve as a prognostic marker in cervical cancer." (PMID 38356704, 2024). "Knockdown of MMP1 could inhibit cervical cancer cell invasion, migration, and proliferation via epithelial-mesenchymal transition." (PMID 32300605, 2020). "In cervical cancer, 10% of patients showed genetic alterations in MMP1." (PMID 32300605, 2020). "Some studies have observed the upregulation of MMP1 in cervical cancer." (PMID 32300605, 2020). "These and our results suggest that a combined FASN and MMP1 inhibition may be beneficial for cervical cancer patients." (PMID 30283446, 2018).
cervical carcinoma (continued). "The five ubiquitination-related biomarkers (MMP1, RNF2, among others) identified herein have potential clinical applications in the diagnosis, prognosis, and therapeutic targeting of cervical cancer." (PMID 40809844, 2025). "Further analysis revealed that MMP14, 23B and 25 were located in significant genomic amplification regions and MMP1, 15, 17 and TIMP1 in all our 6 cervical cancer cell lines." (PMID 29312578, 2017). "In this study, we analyzed the ability of oncoproteins from high-risk HPV16 and HPV18 to transcriptionally regulate 7 types of MMPs (MMP-1, -2, -7, -9, -10, -11 and MT1-MMP) and to correlate MMP expression with cell invasion in cervical cancer cell lines." (PMID 23967226, 2013). "In addition, since MMP-1, -11, -13, -15, -17, -24 and -28 are expressed in all three cervical carcinoma cell lines analyzed, these could be good candidates for further expression analysis in cervical carcinoma tissues as well." (PMID 20942921, 2010). "Furthermore, the upregulation of MMP1, MT1-MMP, MMP2 and MMP9 has been shown to be due to the expression of HPV E6 and E7 oncoproteins in various cellular models of cervical cancer." (PMID 34696321, 2021).
osteosarcoma (23 papers, 2010 to 2025). A usually aggressive malignant bone-forming mesenchymal neoplasm, predominantly affecting adolescents and young adults. "This study highlights that EVs‐derived miR‐1246 promotes osteosarcoma cell migration through activating MMP1 via NamiRNA‐enhancer network dependent on AGO2." (PMID 38585233, 2024). "An in vitro study reported that seahorse hydrolysate has ameliorative effects on MG-63 osteosarcoma cells by reducing matrix metalloproteinases (MMPs), such as MMP-1 and MMP-2." (PMID 35509713, 2022). "Their in vitro trial, proved the antiproliferative usage of a chemically modified tetracycline, against osteosarcoma cells via MMP-1 inhibition." (PMID 32377334, 2020). "To identify the mediator of MCP-1-promoted osteosarcoma migration, we further examined the expression of MMP-1, MMP-2, MMP-3, MMP-7, MMP-9, MMP-12, and MMP-13 mRNA under MCP-1 stimulation." (PMID 33228783, 2020). "To identify the mediator of TSP‐2‐promoted osteosarcoma migration, we examined levels of MMP‐1, MMP‐2, MMP‐3, MMP‐7, MMP‐9, MMP‐12 and MMP‐13 mRNA expression following TSP‐2 stimulation." (PMID 33021341, 2020). "MMP-1 plays an important role in the lung formation of micro- and macro-metastases in patients diagnosed with osteosarcoma." (PMID 32377334, 2020). "In the light of the collagenolytic activity of MT1-MMP, it is noteworthy that another important collagenase, MMP-1, has been shown to be involved in osteosarcoma growth and metastasis in mouse models." (PMID 33154487, 2020). "For example, the expression of various MMPs, such as MMP-1 and MMP-2 was associated with poor prognosis in osteosarcoma and soft tissue sarcoma." (PMID 29316907, 2018). "AP-1 (Fra-1/c-Jun) mediated induction of MMP-1,2 were required for invasion of osteosarcoma cells and angiogenesis of human dermal microvascular endothelial cells (HDMVECs)." (PMID 27626695, 2016). "Cell migration and invasiveness of osteosarcoma cells is known to be promoted by the upregulation of the expression of matrix metalloproteinase-1 (MMP-1) through activation of activator protein-1 (AP-1) transcription factors." (PMID 26264004, 2015). "Previous studies showed significant expression of MMP-1, -2, -3, -8, -9, and -13 in human osteosarcoma cells, and also indicating that these MMPs participated the progression and metastases in human osteosarcoma." (PMID 25003330, 2014). "Therefore, we evaluated MMP1 mRNA expression in seven osteosarcoma cell lines, including HOS and HOS-143B." (PMID 40779492, 2025). "MMP1 showed the highest expression in HOS-143B cells among all osteosarcoma cell lines." (PMID 40779492, 2025). "Instead, miR‐1246 inhibitors could reduce the MMP1 expression, highlighting its specific regulation on MMP1 in osteosarcoma." (PMID 38585233, 2024). "Indeed, osteosarcoma-derived extracellular membrane vesicles (EMVs) convey bioactive pro-osteoclastogenesis factors (as MMP-1 and -13, TGF-β, CD-9 and RANKL) responsible in stimulating osteoclast formation and bone resorption." (PMID 34950663, 2021). "Thus, Fxol showed promising anti-metastatic activities on osteosarcoma cells by blocking AP-1, resulting in inhibition of MMP-1." (PMID 26264004, 2015). "Instead, MMP1 expression was significantly reduced by miR‐1246 inhibitor treatment in 143B cells, further supporting that miR‐1246 could specifically regulate MMP1 expression in osteosarcoma." (PMID 38585233, 2024). "Therefore, inhibition of CXCR4 in osteosarcoma decreases invasion and MMP1 expression." (PMID 32863948, 2020). "Besides, it has been already demonstrated that MMP1 could facilitate osteosarcoma formation and its lung metastasis in mouse models in vivo, further supporting that the activation of MMP1 by nuclear miR‐1246 (NamiR‐1246) was vital for osteosarcoma metastasis." (PMID 38585233, 2024). "Studies have revealed that MMPs including MMP-1, MMP-2, MMP-3, MMP-7, MMP-9, MMP-12, and MMP-13 are significantly related to osteosarcoma metastasis and poor prognosis." (PMID 33228783, 2020).
osteosarcoma (continued). "Triggered expression of RUNX2 by Wnt/B-catenin signaling was shown to promote the expression of several genes such as MMP1 and MMP2 that promote cell migration and metastasis in osteosarcoma by remodeling the extracellular matrix." (PMID 32695811, 2020). "In osteosarcoma, KRAS inhibition decreased MMP1, MMP9, and AKT/ETS1 signaling." (PMID 40779492, 2025). "Furthermore, the upregulation of matrix metallopeptidase genes, including MMP1, MMP2, MMP9, MMP11, and MMP16, has been observed in osteosarcoma (OS)." (PMID 38966281, 2024). "Furthermore, lnc-KASRT overexpression increased KLF6-SV1, MMP1, and MMP9 expression and decreased SRSF1 and KLF6-WT expression in osteosarcoma mice, but lnc-KASRT downregulation showed the opposite trend." (PMID 34568030, 2021). "MMP-1 (also known as collagenase-1) has been found to be markedly upregulated after intra-tibial injection of 143B highly metastatic human osteosarcoma cells into SCID mice compared with injection of a non-metastatic HOS cell line." (PMID 32377334, 2020). "RT-PCR validation of predicted miRNA targets revealed an increase in the expression of matrix metalloproteinase (MMP1) and focal adhesion kinase (PTK2), implicating EV-mediated miRNA transfer in high grade, aggressive osteosarcomas, in agreement with previous observations." (PMID 27812189, 2016). "In line with the biological function of miR‐1246 on osteosarcoma metastasis, knockdown of MMP1 in 143B cells inhibited the primary osteosarcoma metastasis in the lungs while MMP1 overexpression in nonmetastatic HOS cells facilitated the lung metastasis of osteosarcoma." (PMID 38585233, 2024).